RET (ret proto-oncogene)
Diseases named in the same sentence as RET in open-access papers (continued):
Sharing a sentence is not in itself a finding about the gene and the disease.
colorectal cancer (42 papers, 2012 to 2025). A primary or metastatic malignant neoplasm that affects the colon or rectum. "Increasingly, whole genome profiling or focused mutation panels are identifying RET rearrangements in colorectal cancers similar to those in thyroid and lung." (PMID 30666215, 2018). "RET promoter CpG island methylation is associated with a poor prognosis in stage II colorectal cancer, but RET fusion kinases has also been identified." (PMID 27481518, 2016). "The 2024 V1 version of the colorectal cancer NCCN guidelines includes RET fusion genes as recommended biomarkers for testing." (PMID 40308511, 2025). "Other emerging biomarkers such as POLE/POLD1 and RET, though still in early validation phases, have expanded stratification and therapeutic approaches for colorectal cancer patients." (PMID 40308511, 2025). "RET fusions are found in <1% of colorectal carcinomas, mainly CCDC6–RET and NCOA4–RET, with rarer partners such as TNIP1, SNRNP70, GEMIN5, and RRBP1." (PMID 41465145, 2025). "In large cohort studies, RET fusions have been identified in less than 1% of colorectal cancer cases." (PMID 39590164, 2024). "All these kinases displayed mutations in more than 6% of CDX2-suppressed colorectal cancers in the TCGA cohort, and some receptor tyrosine kinases, including EGFR, ERBB3, ERBB4, RET, ROS1, and ALK, showed even higher mutation rates in these cancers." (PMID 39452477, 2024). "Overexpression of GNG10 promotes colorectal cancer progression, and we found that GNG10 expression was higher in the RET Null, suggesting an association between GNG10 and HSCR." (PMID 37144136, 2023). "Increased expression of GDNF enhances β1 integrin expression via signaling through RET/GFRα1 in colorectal cancer cell lines, thus strongly influencing adhesion to and invasion of the extracellular matrix (ECM)." (PMID 35582425, 2022). "The overall prevalence of RTK fusions in colorectal cancers was 1.0%, with the top frequent fusion genes being RET (0.34%), ALK (0.19%), and NTRK1 (0.10%)." (PMID 36369474, 2022). "FGFR1 has been reported to have both oncogenic and tumor suppressive potential and the tyrosine kinase RET has long been established as a classic proto-oncogene but was found to act as a TSG in colorectal carcinomas." (PMID 36726722, 2022). "In conclusion, the results from this study suggested that, firstly, RET is involved in the pathogenesis of colorectal cancer." (PMID 33906292, 2021). "It has been recently reported that RET is methylated in 63% of colorectal cancers and that, in 27% of colon adenomas, RET is in the methylated format." (PMID 33906292, 2021). "For example, RET is altered in 2.94% of colorectal carcinoma patients and, further, PI3K signaling can be activated by direct mutation or amplification of PIK3CA or loss of PTEN." (PMID 34885128, 2021). "On one hand, it has been proposed that RET is a potential tumor suppressor gene in colorectal cancer." (PMID 29665843, 2018). "XB130 was found in colorectal cancer cells as a Src family kinase target, and then found as a target of RET/PTC oncogenic kinase in thyroid cancer cells." (PMID 27029000, 2016). "We recently described RET promoter CpG island methylation as a potential prognostic marker in stage II colorectal cancer (CRC) patients of two independent series." (PMID 27118999, 2016). "Evidence of therapeutic response in CRC patient with a CCDC6-RET fusion treated with the RET kinase inhibitor regorafenib highlights the therapeutic importance of genomic profiling in colorectal cancer." (PMID 26078337, 2015). "The aberrant methylation of RET correlates with decreased RET expression, whereas the restoration of RET in colorectal cancer cell lines results in apoptosis." (PMID 23109895, 2012). "However, a study conducted in colorectal cancer demonstrated that the CCDC6::RET fusion is mutually exclusive with other important driver mutations, such as KRAS, BRAF and PIK3CA." (PMID 39684377, 2024).
colorectal cancer (continued). "Extrapolating from these results, targeted therapies against RET fusions could be a promising area for further clinical research in colorectal cancer." (PMID 38790167, 2024). "RET fusions have been identified in <1% of colorectal carcinomas (CRC)." (PMID 32326537, 2020). "The effects of GFL-mediated RET activation in colorectal cancer are less clear." (PMID 30666215, 2018). "Moreover, although RET mutations (V145G, R360W or G593E) in colorectal cancer have been identified and are reported in the COSMIC database, these mutations apparently inactivate RET." (PMID 29665843, 2018). "Notably, RET promoter methylation is associated with poor prognosis in stage II and III colorectal cancer patients." (PMID 29665843, 2018). "Unexpectedly, RET is methylated in 27% of colon adenomas and in 63% of colorectal cancers." (PMID 23109895, 2012). "A multicenter, phase 1/2, basket study published in Nature Medicine included 45 patients with RET gene fusions (including 10 patients with colorectal cancer) and found significant anti-tumor activity of Selpercatinib in patients with RET fusion-positive advanced colorectal cancer." (PMID 40308511, 2025). "Therefore, it is expected that RET gene becomes downregulated in colorectal cancer (CRC)." (PMID 33906292, 2021). "Results demonstrated here align with emerging data on selpercatinib’s efficacy across diverse RET-altered tumors, including NSCLC, colorectal cancer, salivary gland cancer, pancreatic adenocarcinoma and glioblastoma, thereby indicating its broad applicability." (PMID 39085487, 2024). "In colorectal cancer (CRC), only a small fraction of tumors (< 1%) harbors a RET fusion of RET exon 11 or 12 with the most common being NCOA4::RET and CCDC6::RET fusions." (PMID 38539256, 2024). "RET fusions are not common in colorectal cancer, accounting for less than 1%, but research on this mechanism is relatively abundant." (PMID 40308511, 2025). "However, the objective response rate was the lowest among entrectinib‐treated NTRK+ colorectal cancer (CRC) (20%) and selpercatinib‐treated RET+ CRC (20%) among all NTRK+, and RET+ solid tumors, respectively." (PMID 39950716, 2025). "Similarly, in colorectal cancer cell lines, β1 integrin expression is enhanced by increased GDNF expression via signaling through RET/GFRα1, notably influencing adhesion to and invasion of the ECM." (PMID 35582425, 2022). "On the other hand, Le Rolle and co-workers have recently reported on the identification and characterization of RET fusions that juxtapose the C-terminal RET kinase domain to the N-terminal domain of CCD6 or NCOA4 (CCDC6-RET and NCOA4-RET fusions) in advanced colorectal cancer." (PMID 29665843, 2018). "Thus, further investigation is required to establish significance of RET and GFL activity in colorectal cancer." (PMID 30666215, 2018). "The availability of NGS facilitates a therapeutic genomic paradigm to classify CRC based on actionable genomic biomarkers such as RET, ALK, NTRK, ROS and ERBB2, which may facilitate the clinical trial development of a Colorectal Cancer Genomic Protocol." (PMID 26078337, 2015). "It was reported that the treatment of refractory colorectal cancer with regorafenib, an inhibitor of multiple kinases, including vascular endothelial growth factor receptor (VEGFR) 1–3, Tie2, KIT, platelet derived growth factor receptor and RET, achieved a 6% partial response and 23% stable disease." (PMID 31769426, 2019).
paraganglioma (37 papers, 2012 to 2026). A benign or malignant neoplasm arising from paraganglia located along the sympathetic or parasympathetic nerves. "Most genetic studies on paraganglioma patients have highlighted the germline mutations in the RET, NFI and SDH mutations." (PMID 30366175, 2018). "Germline mutations have been identified in paragangliomas involving the proto-oncogene RET, tumor suppressor genes VHL, and NF1 The commonest clinical presentation is hypertension but incidentally detected forms have been reported during imaging and on a few occasions the diagnosis was missed." (PMID 36591002, 2022). "A RET mutation was previously detected in a patient with multiple paragangliomas." (PMID 33391357, 2020). "In addition, in this family, the RET mutation was observed in the male adult with bilateral carotid body and jugulotympanic paragangliomas and his son with unilateral CPGLs." (PMID 33391357, 2020). "Thus, HIF2A currently represent the second most frequent mutated gene (after the RET gene) associated with paragangliomas." (PMID 28187001, 2017). "Approximately 25% to 35% of paragangliomas are often associated with hereditary conditions such as MEN type 2, von Hippel-Lindau syndrome, or mutations in the SDHB, SDHD, or RET gene." (PMID 39867070, 2024). "RET and VHL are HSP90 clients, and it has been reported that the expression of HIF-1α and HIF-2α (an HSP90 client) were implicated in the pathogenesis of paraganglioma with SDHB and SDHD mutations." (PMID 35932386, 2022). "Moreover, the likely pathogenic germline variant NM_020975: c.A2372T, p.Y791F (chr10: 43613908, rs77724903) in RET was identified in two out of four members of a family with multiple and malignant paragangliomas." (PMID 33391357, 2020). "Additionally, in several recorded cases, paragangliomas violated the “mutual exclusion of mutations” rule: these tumors simultaneously carried somatic mutations in the NF1 gene and in the RET or VHL genes." (PMID 28187001, 2017). "Functioning SDHx paragangliomas sometimes release dopamine and/or norepinephrine, originating raised plasma levels of methoxytyramine, contributing to distinguish SDHx patients from those with VHL, RET, or NF1 mutations." (PMID 24899893, 2014). "However, no such impairments were detected resulting from the RET activating mutations associated with paragangliomas." (PMID 28187001, 2017).
pancreatic cancer (34 papers, 2008 to 2026). "GDNF accelerates the migration of Kras-mutated pancreatic cancer cells to nerve cells through the RET–phosphatidylinositol 4,5-diphosphate-3-kinase catalytic pathway." (PMID 39119085, 2024). "This suggests a direct correlation between the G691S RET single nucleotide polymorphism and the aggressive growth of pancreatic cancers." (PMID 38099290, 2023). "Additionally, RET has also recently been implicated in the progression of both breast and pancreatic tumours." (PMID 26874741, 2016). "This discrepancy underscores the potential clinical significance of identifying RET fusions in pancreatic cancer despite their overall low prevalence and suggests a possible avenue for targeted therapy in this subset of patients." (PMID 39085487, 2024). "While RET fusion is rare (0.6%) in pancreatic cancer, the efficacy of RET-targeted treatment in patients with TRIM33-RET fusion has not been previously reported." (PMID 37139148, 2023). "BLU-667 is a highly specific RET inhibitor developed for the treatment of tumors with RET mutations and rearrangements, including NCOA4-RET and CCDC6-RET fusions, as observed in two of the analyzed pancreatic tumors." (PMID 33441414, 2021). "We demonstrated a novel regulatory mechanism for GDNF/GFRα1/RET/Src axis by APE1 in pancreatic cancer cell growth." (PMID 32438692, 2020). "Taken together, APE1-induced GFRα1 allows pancreatic cancer cell proliferation through RET/Src/ERK cascade signaling in the response to GDNF." (PMID 32438692, 2020). "It is also expressed in pancreatic cancers together with the GDNF receptor RET, and this expression correlates with intrapancreatic neural invasion." (PMID 32438692, 2020). "Except for these four driver genes, more and more genes are identified as the critical genes in the process of pancreatic cancer, including ret proto-oncogene (RET), AT-rich interaction domain 1A (ARID1A), and ATM." (PMID 31552163, 2019). "GFL and RET expression are correlated with perineural invasion and resultant increased pain levels in pancreatic cancer patients." (PMID 30666215, 2018). "RET fusions have shown sensitivity to selpercatinib and pralsetinib, both of which are selective RET inhibitors approved in other cancers and are currently under investigation in pancreatic cancer." (PMID 40806185, 2025). "Moreover, enhanced secretion of GDNF by cells within the tumor microenvironment stimulates RET activity in pancreatic tumor cells, thus exerting a paracrine effect on pancreatic cancer cells to drive perineural invasion." (PMID 35957881, 2022). "Moreover, GDNF induces perineural invasion in pancreatic cancers, and inhibition of RET signaling suppressed perineural invasion." (PMID 22745701, 2012). "In addition to pancreatic cancers, RET is altered in ~1.2% of ovarian cancers." (PMID 35957881, 2022). "Therapeutic approaches targeting RET with small-molecule kinase inhibitors are being evaluated for cancers that are associated with RET mutations or increased RET expression, such as MTC, chronic myelomonocytic leukaemia (CMML), and breast and pancreatic cancers 16-18." (PMID 31534554, 2019). "There is no information as to whether the Y791F mutation was germline or somatic in this patient, but as KRAS G12D is a very well-described pancreatic cancer-driver mutation, the results strongly indicate a minor/non-pathological role for RET Y791F." (PMID 25425582, 2015). "The RET protein tyrosine kinase receptor for GDNF is overexpressed in human neuroplexi tissues and is present in several pancreatic cancer cell lines." (PMID 39346791, 2024). "This leads to phosphorylation of RET and subsequent activation of extracellular signal-regulated kinases (ERK) in PDAC tumor cells, ultimately promoting the perineural invasion of pancreatic cancer cells." (PMID 38099290, 2023). "RET alterations occur in ~1.9% of pancreatic cancers whereas wild-type RET, co-receptor GFRα1, and GDNF are overexpressed in 50-70% of pancreatic cancer cases." (PMID 35957881, 2022).
pancreatic cancer (continued). "The discovery of recurrent fusions involving NRG1 in KRAS wild-type pancreatic tumors, as well as case reports of fusions involving BRAF, PRKACA, NTRK1/3, and RET, prompted us to systematically screen for fusion genes in this cancer entity." (PMID 33441414, 2021). "In pancreatic cancers, GDNF/GFRα1/RET is expressed more robustly than in normal pancreatic tissue and benign tumors." (PMID 32438692, 2020). "In the last decade, several studies attempted to demonstrate the connection between polymorphisms of angiogenesis-related factors (VEGF, VEGFR-2, RET, EGF, TGF-β) genes and pancreatic tumours." (PMID 28218664, 2017). "A novel multikinase inhibitor of MET, VERFR1, AXL, TIE2, KIT, FLT3, and RET, called cabozantinib (also known as XL184), inhibits the growth, metastasis, and angiogenesis in pancreatic cancer and glioblastoma, and reduces resistance to gemcitabine." (PMID 26225770, 2015). "As a ligand for the RET proto-oncogene, GDNF would be a likely candidate for promoting cancer progression, and has been proposed to do so in pancreatic cancer." (PMID 18616821, 2008). "In pancreatic cancer cell lines, glucose concentration tends to alter the cell proliferation in a concentration dependent manner through the expression of GDNF (glial cell line derived neurotrophic factor) and RET (tyrosine kinase receptor)." (PMID 40735043, 2025). "Additionally, Ceyhan and colleagues demonstrated that RET activation by another GFL, Artemin, can promote invasion and migration of pancreatic cancer cells." (PMID 35957881, 2022). "When applied to a large collection of published pancreatic cancer samples (n = 803), Arriba identified a variety of driver fusions, many of which affected druggable proteins, including ALK, BRAF, FGFR2, NRG1, NTRK1, NTRK3, RET, and ROS1." (PMID 33441414, 2021). "Pancreatic cancer is a heterogenous disease with multiple exomic genetic alterations in about 12 key cellular signaling pathways (e.g., Poly (ADP-ribose) polymerase inhibition, CD40 activation, hedgehog signaling inhibition, and RET inhibition)." (PMID 29361690, 2018). "Also, in the case of pancreatic cancer, guidelines recommend the study of rare gene fusions such as NTRK and RET, which, although uncommon, may offer access to highly effective targeted therapies." (PMID 41153346, 2025).